USP7 (ubiquitin specific peptidase 7)
Diseases named in the same sentence as USP7 in open-access papers (continued):
Sharing a sentence is not in itself a finding about the gene and the disease.
tumor (continued). "Furthermore, USP7 was reported not only could take part in p38 MAPK pathway to influence tumor growth but also regulate PD-L1 expression in tumor and its growth environment." (PMID 38240708, 2024). "Therefore, regulating the expression and activity of USP7 in tumor inflammatory responses could be a potential therapeutic strategy." (PMID 39767641, 2024). "Hence, this might be attributed to USP7’s ability to deubiquitinate and stabilize PD-L1, consequently playing a role in tumor immune evasion." (PMID 39748950, 2024). "Furthermore, the role of USP7 may differ in different tumor types, which requires further experimental data." (PMID 39767641, 2024). "In addition, USP7 could also become a potential target for tumor treatment by inhibiting the activity of USP7 to suppress the occurrence and development of tumors." (PMID 39767641, 2024). "Therefore, combining USP7 inhibitors with PARP inhibitors might yield a more potent anti-tumor response than using PARP inhibitors alone, potentially offering a more effective treatment approach for PC." (PMID 39048965, 2024). "Hence USP7 may assist in stabilizing PD-L1 protein levels, potentially playing a role in tumor immune evasion." (PMID 37658402, 2023). "USP7 may have context-dependent oncogenic effects in addition to tumor suppressive functions." (PMID 37605223, 2023). "We hypothesized that inhibition of USP7 would be effective against NB tumor growth." (PMID 37762082, 2023). "We asked if treatment of USP7 inhibitor to germline mutant Apcmin mice will be less efficacious in suppressing USP7 function than genetic deletion, hence offering a potential therapeutic window to suppress tumor growth without causing gut inflammation." (PMID 36669491, 2023). "It has been suggested that these adipocyte derived EVs might promote tumor growth through inducing cell proliferation by decreasing the level of the anti-tumor miRNA-34a and upregulating the pro-cancer ubiquitin-specific peptidase 7/Cyclin A2 signaling pathway (USP7/CCN2A)." (PMID 37240762, 2023). "In addition, increased USP-7 expression generally indicates a poor tumor prognosis." (PMID 37298148, 2023). "Thus, it would be clinically relevant to investigate whether the USP7-cyclin F axis contributes to tumor progression and aggressiveness in these specific contexts." (PMID 36342772, 2022). "Therefore, USP7 inhibition in combination with other therapeutic approaches not only has a synergistic impact that improves the treatment efficacy, but also helps overcome tumor chemoresistance." (PMID 36428632, 2022). "However, the specific contribution of USP7 to tumor progression is largely unexplored." (PMID 33849069, 2021). "So, our hypothesis is that USP7 plays a tumor-promoting role in OSCC." (PMID 34812471, 2021). "Also, the increased USP7 expression often indicates a poor tumor prognosis." (PMID 33967786, 2021). "Therefore, in this review, we will start from the structure and function of USP7, reveal the inextricable connection between USP7 and tumor resistance, and propose that targeting USP7 might be a new insight to overcome drug resistance." (PMID 33967786, 2021). "Therefore, targeting USP7 can significantly activate systemic anti-tumor immune response." (PMID 32802195, 2020). "However, the deubiquitinase USP7 has many substrates including several tumor suppressors and CCDC6, the tumor suppressor whose reduced levels impair HR DNA repair and sensitize cancer cells to treatment with PARP inhibitors, as reported in several malignancies." (PMID 31242618, 2019). "Furthermore, small molecules antagonistic to USP7 may function as anticancer agents, targeting certain tumor types." (PMID 30319415, 2018).
tumor (continued). "Hence, inhibition of USP7 may provide dual anti-tumor activities—direct tumoricidal effects and immune-mediated tumor elimination." (PMID 29236775, 2017). "Therefore, increased MLL5 protein via upregulation of OGT and USP7 in tumor cells may contribute to altered cell proliferation and malignant transformation." (PMID 26678539, 2015). "USP7 inhibitor P22077 significantly attenuates ETV4-MAPK7-induced cell proliferation in vitro and tumor growth in vivo." (PMID 42100492, 2026). "In this study, the roles of DACH1 and USP7 in CRC and their post-translational regulatory mechanisms were explored, revealing their significant roles in tumor development." (PMID 40389405, 2025). "Collectively, these findings establish that USP7 deubiquitinates and stabilizes DDR1, and that USP7 inhibition promotes DDR1 ubiquitination and degradation, ultimately suppressing tumor cell proliferation both in vitro and in vivo." (PMID 40713963, 2025). "In CRC, USP7 also plays a key role in regulating YY1 protein levels, which promote tumor development." (PMID 40568598, 2025). "USP7 knockout leads to a marked decrease in the expression of stemness‐related molecules CD133 and Nanog, along with a significant reduction in tumour sphere formation." (PMID 40078091, 2025). "USP7 was identified as a deubiquitinase that stabilizes DACH1, enhancing its tumor-promoting activities." (PMID 40389405, 2025). "Preclinical experiments confirm that targeting ferroptosis-related pathways (such as the USP7/SCD axis and ABCC2-mediated glutathione efflux) effectively inhibits tumor growth and metastasis." (PMID 40861444, 2025). "This study elucidates the critical roles of USP7 and DACH1 in CRC, revealing their involvement in tumor progression and potential as therapeutic targets." (PMID 40389405, 2025). "By reducing Raf-1 activity, USP7 blocks the ERK signaling pathway, thereby regulating the tumor proliferation of NSCLC." (PMID 41157055, 2025). "USP7 is also identified as a crucial role on YAP in the regulation of CRC cell proliferation and tumor growth." (PMID 40568598, 2025). "A11 competitively binds PD-L1, inhibiting USP7-mediated deubiquitination, which leads to increased PD-L1 degradation and improved CD8+ T cell–mediated tumor cell killing, resulting in synergistic antitumor effects when combined with PD-1 blockade." (PMID 41359051, 2025). "We herein identified a sustained USP7 expression that, transcriptionally activated by FUBP1 and FUBP3, is essential for HIF2α stabilization and tumor progression in ccRCC." (PMID 39406703, 2024). "Other USP7 inhibitors, such as P22077, X36, YCH2823, and FT-671, have all demonstrated anti-tumor activity and are currently in preclinical trial stages." (PMID 39223632, 2024). "Mechanistically, USP7 expression is activated by the transcription factors FUBP1 and FUBP3, and it promotes tumor progression mainly by deubiquitinating and stabilizing HIF2α." (PMID 39406703, 2024). "Ubiquitin-specific protease 7 (USP7), a member of the DUB family, exhibits a wide range of substrates, including key proteins involved in tumor suppression, DNA repair, and immune responses." (PMID 39767641, 2024). "usp7 promotes the entry of CAF-derived miR522 into the exosome by stabilizing hnRNPA1 through deubiquitination, which regulates tumor progression through the usp7/hnRNPA1 axis." (PMID 39253578, 2024).
tumor (continued). "In CRC, only a limited number of studies addressed the role of USP7 in enhancing the stem cell property of cancer cells by stabilizing JUND (JunD proto-oncogene) and promoting tumor development by mediating the stability of β-catenin." (PMID 38769122, 2024). "In mice, inhibition of USP7 activates the p38-MAPK signaling pathway, promoting the transformation of TAMs into the M1 phenotype and inhibiting tumor progression." (PMID 39223632, 2024). "Nevertheless, the role of USP7 and MTDH in the tumor microenvironment still needs further investigate in immune-competent mouse model to identify their effects in immunoregulation." (PMID 38625581, 2024). "USP7 inhibition affects HIF‐1α transcriptional modulation, tumor hypoxia and remodeling of the tumor microenvironment creating a permissive immune micro‐climate for infiltrating lymphocytes turning immunologically ‘cold’ tumors, ‘hot’." (PMID 38602256, 2024). "This study demonstrated that, in the nucleus, USP7 downregulates DICER at the protein level, forming a new regulatory axis that impairs DNA damage response and then promotes tumour growth." (PMID 37867415, 2024). "Subsequently, virtual screening and cell-function assay were performed to screen the USP7 inhibitors for regulating YY1 expression and inhibiting tumor progression." (PMID 37408047, 2023). "In addition, chemotoxicity affects tumor growth and attenuates cisplatin chemotherapeutic efficacy by boosting miR-522 release from CAFs through triggering the USP7/hnRNPA1 pathway, whereas preventing miR-522 secretion could inhibit tumor growth and enhance sensitivity to cisplatin." (PMID 37213276, 2023). "Twelve of the ninety-nine DUB genes were identified as differentially expressed in MB compared to non-tumor tissue (p < 0.0001) for the GO category of DNA repair in the Swartling dataset, including USP1, OTUB1, UCHL5, USP7, and PSMD14 (aka POH1)." (PMID 37892185, 2023). "Most importantly, the USP7 inhibitor sensitizes tumor cells to chemotherapy by decreasing SAMHD1, which implies the potential of targeting USP7-SAMHD1-CtIP axis to improve chemosensitivity." (PMID 37081042, 2023). "The USP7/c‐Abl axis promotes NSCLC cell glycolysis process by stabilizing hexokinase‐2 (HK2) protein, therefore promoting NSCLC tumour progression." (PMID 38082439, 2023). "IHC results showed that USP7 and YY1 expression levels were higher in tumor tissues than in normal liver tissues." (PMID 37408047, 2023). "IHC staining was performed to detect the expression levels of USP7, YY1, E-cadherin, and vimentin in tumor tissues." (PMID 37408047, 2023). "Our data demonstrated that ENKUR induced by CB suppresses HCC malignant activities via antagonizing β-catenin/c-Jun/MYH9/USP7/c-Myc-stimulated cell cycle and EMT pathways, which indicated the significance of ENKUR as a tumor suppressor in HCC." (PMID 35414777, 2022). "USP7 inhibition leads to TAM polarization towards pro-inflammatory M1 macrophages, potentiating anti-tumor immune responses." (PMID 36428632, 2022). "It has been reported that USP2a, USP7, USP21, and USP22 are highly expressed in the HCC tissue or cells and promote tumor development." (PMID 35669517, 2022). "In supporting this, USP7 deubiquitinates and stabilizes well-established oncogenes such as HIF-1α and N-Myc to facilitate tumor progression." (PMID 35931679, 2022). "Both USP7 and TAZ proteins were significantly upregulated in HNSCC as compared to their non-tumor counterparts." (PMID 35931679, 2022).
tumor (continued). "Our results demonstrated pharmacological inhibition of USP7, which further downregulated ABCB1 expression, suppressed tumor growth, and considerably restored the effectiveness of doxorubicin and paclitaxel." (PMID 36291159, 2022). "As expected, USP7 inhibitors (like P5091) can downregulate CCDC6 protein levels and favor tumor cells sensitivity to PARP inhibitors in non-small cell lung cancer, lung neuroendocrine cancer and hormone-sensitive and castration-resistant prostate cancer." (PMID 33967786, 2021). "Studies have also shown that USP7 participates in the stabilization of anti-apoptotic protein MCL-1, leading to the upregulation of MCL-1 levels in tumor cells." (PMID 34869041, 2021). "USP7 is the most widely studied DUB and considered to be an oncogene as it promotes tumor growth and negatively affects patient’s immune response to tumors." (PMID 33805973, 2021). "Phosphorylated USP7 gains increased deubiquitinating activity, thus promoting the nuclear exclusion of phosphatase and tensin homolog (PTEN), which disrupts PTEN’s tumor suppressive function in CML cells." (PMID 34454635, 2021). "USP7, as a deubiquitinating enzyme (DUB), participates in regulating many cellular process, including tumor progression, immune dysfunction, DNA damage, and epigenetic regulation." (PMID 33869052, 2021). "Our study unveiled the synergistic effect of USP7 haploinsufficiency with aberrant TAL1 activation on T-ALL, implicating USP7 as a haploinsufficient tumor suppressor in T-ALL." (PMID 33664368, 2021). "It was demonstrated that concomitant USP7 and JMJD3 inhibition lead to a reduction of tumor growth in vivo." (PMID 33478063, 2021). "TRIM44, USP20 and USP7 also stabilizes HIF-1α by deubiquitination, leading to tumor progression under hypoxia." (PMID 33004065, 2020). "In order to test our proteomics observations in a larger cohort of patient samples, we analyzed the expression of HUWE1, USP9X and USP7 in protein lysates isolated from fresh frozen PTC patient samples (7 normal, 8 tumor, 3 metastatic lesions)." (PMID 32345963, 2020). "The levels of USP7 and mitotic markers, including AURKB, CCNB1, and PLK1, were higher in tumor samples than in normal tissues." (PMID 33207738, 2020). "Several studies implicate USP4, USP7, USP6, USP15, USP16, USP42, and USP28 as oncogenes, whereas CYLD, A20, and BAP1 act as tumor suppressors." (PMID 32549302, 2020). "Targeted inhibition of USP7 reprogrammed TAMs to M1 MΦs by activating p38 MAPK pathway, and then activated the anti-tumor effect mediated by CTL, and finally inhibited tumor growth." (PMID 32802195, 2020).
tumor (continued). "USP7 is known to regulate drug resistance by stabilizing its targets, which include a range of oncogenes and tumor suppressors, NEK2 is one of the USP7 targets." (PMID 31955515, 2020). "Since USP7 inhibitors are developed primarily for oncology, a more viable approach to use USP7 inhibitors as senolytic agents may be to clear SnCs induced by chemotherapy because such cells can contribute to chemotherapy‐induced toxicity and promote tumor relapse and metastasis in part via the SASP." (PMID 32064756, 2020). "The deubiquitylating enzyme USP7 is known to stimulate the DNMT1 activity, and conversely, USP7-siRNA reduces DNMT1 activity and decreases tumor cell viability." (PMID 30786932, 2019). "Thus, contrary to initial reports, high levels of USP7 may promote tumor progression." (PMID 25519684, 2015). "The knockdown of USP7 in NSCLC cells impaired cell invasion and motility, and tumor formation, and induced cell apoptosis." (PMID 25519684, 2015). "USP7 helps in removing mono-Ub link on PTEN, facilitating its translocation back to the cytosol, which enhances tumor aggressiveness in PCa." (PMID 25121098, 2014). "However, considering the genomic instability derived from USP7 depletion, the current study may suggest that a combination of USP7 inhibitors with DNA damaging agents may represent a successful strategy in killing tumor cells." (PMID 25003721, 2014). "Additionally, the tumor-promoting effect of Usp7-OE was counteracted by Pdl1-KO, suggesting that STS exerted its effects by inhibiting USP7, thereby reducing PDL1 expression and enhancing the sensitivity of tumor cells to T cell-mediated killing." (PMID 40365281, 2025). "Furthermore, USP7 can bind to Lysine-specific histone demethylase 1A (LSD1), which further increases the proliferation of the tumor." (PMID 41157055, 2025). "USP7 was also shown to stabilize HK2 protein, therefore promoting NSCLC tumor progression." (PMID 40006058, 2025). "Further mechanism studies showed that LRRC1 enhances PDK1 stability by promoting its deubiquitination via USP7, thereby increasing AKT1 phosphorylation levels and activating the AKT/GSK3β/β-catenin/VEGFA signaling pathway, ultimately accelerating tumor angiogenesis in HCC." (PMID 41369408, 2025). "USP7 is highly expressed in tumor-promoting M2 macrophages, while it is absent in tumor-suppressing M1 macrophages." (PMID 41157055, 2025). "HAUSP (USP7), a deubiquitinating enzyme, can both deubiquitinate HIF‐1α to increase its stability and interact with CBP to mediate the acetylation of H3K56, enhancing the transcription of HIF‐1α and thereby inducing tumour EMT." (PMID 39778006, 2025). "Inhibition of USP7 activates the p38 MAPK pathway, reprogramming M2 macrophages to M1, increasing CD8+ T cell infiltration, and reducing PD-L1 expression in tumor cells, thereby strengthening anti-tumor immune responses." (PMID 39575419, 2024). "To understand the functional implications of USP7‐mediated modulation of VEGF in the TME, we examined the effect of AD‐04 on proliferation, migration and invasion of the various cellular components of the tumour using live cell time‐lapse imaging." (PMID 38602256, 2024). "Moreover, the combination of USP7 inhibitors and afatinib (an ERBB family inhibitor) coordinately induce cell death and tumor suppression." (PMID 39406703, 2024).